KDM5B (lysine demethylase 5B)
Diseases named in the same sentence as KDM5B in open-access papers (continued):
Sharing a sentence is not in itself a finding about the gene and the disease.
head and neck cancer (2 papers, 2018 to 2020). A primary or metastatic malignant neoplasm affecting the head and neck. "KDM5B overexpression was significantly associated with tumor cell proliferation in head and neck cancer, and KDM5B silencing caused cell growth suppression both in vitro and in vivo." (PMID 32751840, 2020). "Additionally, we found that CD8+ T-cell infiltration was negatively associated with KDM5B, especially in HPV+ head and neck cancer (correlation score −0.458)." (PMID 30080846, 2018). "In human tumors, KDM5B expression is inversely associated with STING expression in multiple cancer types, with the level of intratumoral CD8+ T cells, and with patient survival in cancers with a high level of cytosolic DNA, such as human papilloma virus (HPV)-positive head and neck cancer." (PMID 30080846, 2018). "In HPV+ head and neck cancer, we found significant negative correlation between KDM5B and STING expression, with a Spearman’s correlation of −0.465." (PMID 30080846, 2018). "Lastly, we found a positive correlation between CD8+ T-cell infiltration level and patient survival and a negative correlation between KDM5B expression and patient survival in HPV+ head and neck cancer." (PMID 30080846, 2018).
invasive ductal carcinomas (2 papers, 2011 to 2014). "Given that JARID1b/PLU1/KDM5B has been shown to be expressed in 90% of invasive ductal carcinomas and that KDM5B represses transcription by demethylating H3K4, we examined whether KDM5B associates with EMSY." (PMID 24582497, 2014).
laryngeal squamous cell carcinoma (2 papers, 2020 to 2022). A squamous cell carcinoma that arises from the larynx. "Recently, it was reported that miR-139-3p directly regulates KDM5B (lysine demethylase 5B), a key regulator of histone 3 lysine 4 demethylation in laryngeal squamous cell carcinoma." (PMID 33322675, 2020).
lentivirus infection (2 papers, 2019 to 2021). Virus diseases caused by the Lentivirus genus. "In order to study the effect of KDM5B on the growth of HCC cells, we established a KDM5B knockdown cell line through performing lentivirus infection of the Hep3B cells." (PMID 33829656, 2021).
liver fibrosis (2 papers, 2024 to 2025). "To assess the effect of Kdm5b loss on liver fibrosis, we evaluated fibrosis development by Sirius Red staining." (PMID 40824250, 2025). "We found that Kdm5b KO prevented alcohol-induced liver fibrosis and liver inflammation in female mice." (PMID 40824250, 2025). "Taken together, our data suggest that KDM5B KO prevents liver fibrosis development, preserves liver metabolic function in the presence of alcohol, and prevents AH-like transcriptional changes in the liver." (PMID 40824250, 2025). "Collectively, this suggests that hepatocellular KDM5B greatly contributes to alcohol-induced liver fibrosis development in female mice." (PMID 40824250, 2025). "In summary, KDM5B and KDM5C demethylases prevent liver fibrosis resolution after alcohol cessation in part through suppression of LXR activity." (PMID 37943941, 2024). "We found that hepatocyte-specific Kdm5b KO was as effective as CMV-Cre KO in preventing fibrosis development in alcohol-fed mice after 8 weeks of feeding, and hepatocyte-specific Kdm5b KO greatly reduced liver fibrosis development after 16 weeks as well." (PMID 40824250, 2025).
malignant glioma (2 papers, 2018 to 2019). A grade III or grade IV glioma arising from the central nervous system. "Several histone demethylases, including LSD1, KDM5A, and KDM5B, are upregulated in malignant gliomas, sustaining cell growth, and resistance to chemotherapy." (PMID 29360266, 2018).
metastatic tumors (2 papers, 2015 to 2023). "Interestingly, KDM5B was detected in the cytoplasm at higher levels compared to nuclear staining in metastatic tumors." (PMID 37152294, 2023). "Overall, these findings suggest that KDM5B is crucial for initial AR–dependent tumor growth and could also play a role in metastatic tumors once established." (PMID 37152294, 2023). "Elevated KDM5B cytoplasmic expression was noted in metastatic tumors." (PMID 37152294, 2023).
myeloid malignancies (2 papers, 2021). "The most important variables in the model were age and the expression of KDM5B and LAPTM4B, two genes previously associated with the biology and prognostication of myeloid neoplasms." (PMID 33854980, 2021). "Similar to KDM5A, evidence suggests a pro-leukemic role for KDM5B in myeloid malignancies." (PMID 34944554, 2021).
Myocardial fibrosis (2 papers, 2022 to 2024). "For example, KDM5B is associated with the development of hypertension and is involved in myocardial fibrosis and remodeling." (PMID 38584203, 2024). "Consistent with previous reports on the heart, our data confirm that ATF3, which is a key regulator that is epigenetically suppressed by KDM5B, can inhibit myocardial fibrosis mediated by cardiac fibroblasts in response to ischemic or hypertrophic stress." (PMID 36481938, 2022). "KDM5B knockout improves cardiac remodeling, myocardial fibrosis, and cardiac function." (PMID 38584203, 2024).
myocardial infarction (2 papers, 2022 to 2025). Gross necrosis of the myocardium, as a result of interruption of the blood supply to the area, as in coronary thrombosis. "KDM5B deficiency markedly ameliorated cardiac fibrosis, improved cardiac function, and prevented adverse cardiac remodeling following myocardial infarction (MI) or pressure overload." (PMID 36481938, 2022).
respiratory failure (2 papers, 2013 to 2019). The significant impairment of gas exchange within the lungs resulting in hypoxia, hypercarbia, or both, to the extent that organ tissue perfusion is severely compromised. "We were unable to breed a sufficient number of homozygous knockout mice due to high neonatal mortality resulting from respiratory failure, so the HFD cohort consisted of WT and heterozygous KDM5B-deficient mice." (PMID 31467927, 2019). "Here we show that deletion of the H3K4me2/3 histone demethylase Jarid1b (Kdm5b/Plu1) results in major neonatal lethality due to respiratory failure." (PMID 23637629, 2013).
acute lymphoblastic leukemia (1 paper, 2017). Leukemia with an acute onset, characterized by the presence of lymphoblasts in the bone marrow and the peripheral blood. "A newly published study demonstrated a strong increase in the expression of KDM5B in high-risk B-cell precursor acute lymphoblastic leukemia (B-ALL)compared with normal bone marrow." (PMID 27974677, 2017).
acute monocytic leukaemia (1 paper, 2024). "To determine whether KDM5B is involved in leukocyte‐endothelial adhesion, we used THP‐1 cells (a human acute monocytic leukaemia cell line) and HUVECs to perform an adhesion assay." (PMID 39643939, 2024).
atrial fibrillation (1 paper, 2024). A disorder characterized by an electrocardiographic finding of a supraventricular arrhythmia characterized by the replacement of consistent P waves by rapid oscillations or fibrillatory waves that vary in size, shape and timing and are accompanied by an irregular ventricular response. "Atrial fibrillation was associated with rare variations in 8 genes (TTN, RPL3L, KLF1, TET2, NME3, KDM5B, PKP2, PMVK)." (PMID 38390584, 2024). "Atrial fibrillation (ICD10 code I48) was associated with rare variation in 8 genes (TTN, RPL3L, KLF1, TET2, NME3, KDM5B, PKP2, PMVK)." (PMID 38390584, 2024).
atrial septal defect (1 paper, 2021). Interauricular communication is a congenital malformation characterized by a communication between the atrial chambers of the heart. "In the case of KDM5B (OMIM 618109), it has only been described in the context of a recessive neurodevelopmental phenotype with cases presenting ASD (Atrial septal defects)." (PMID 34324492, 2021).
bipolar disorder (1 paper, 2018). A disorder of the brain that causes unusual shifts in mood, energy, activity levels and the ability to carry out day-to-day tasks. "In addition, genes linked to ID (TCF4, CPLX1, CDK6, KDM5B), ASD (RORA, KDM5B), and bipolar disorder (ZNF804A) were also among the 16 differentially expressed target genes." (PMID 29665782, 2018).
Epileptic spasm (1 paper, 2024). A sudden flexion, extension, or mixed extension-flexion of predominantly proximal and truncal muscles that is usually more sustained than a myoclonic movement but not as sustained as a tonic seizure. "Notably, two individuals carrying KDM5B variants show epileptic spasms and/or generalized seizures, although the latter is more likely associated with a deficit in Nav1." (PMID 38575342, 2024).
female infertility (1 paper, 2020). Diminished or absent ability of a female to achieve conception. "In this regard, it is important to mention that the disruption of histone demethylases during mouse oogenesis [including lysine-specific demethylase 5B (Kdm5b)] has also been associated with meiotic defects and female infertility." (PMID 32134918, 2020).
heart failure (1 paper, 2022). Inability of the heart to pump blood at an adequate rate to meet tissue metabolic requirements. "KDM5B drives the progression of cardiac fibrosis and facilitates adverse cardiac remodeling in response to ischemic or hypertrophic stress, which will aid in the development of novel epigenetic therapies for pathological cardiac fibrosis and heart failure." (PMID 36481938, 2022).
Hypoglycemia (1 paper, 2019). A decreased concentration of glucose in the blood. "Interestingly, insulin tolerance test (ITT) showed that recovery after hypoglycemia was delayed in KDM5B-KO mice (p < 0.05), supporting that KDM5B-KO mice maintain normoglycemia through improved insulin sensitivity." (PMID 31467927, 2019).
Luminal breast cancer (1 paper, 2015). "Notably, H3K4 demethylase KDM5B (also known as JARID1B), which is localized at 1q32.1, was recently shown to be an oncogene in Luminal breast cancer by regulating lineage-specific genes." (PMID 25537518, 2015).
lung fibrosis (1 paper, 2023). "Finally, GAS5 overexpression attenuated lung fibrosis in bleomycin-induced mice by regulating the KDM5B/PDGFR α/β signaling pathway." (PMID 36918759, 2023).
lung squamous cell carcinoma (1 paper, 2020). "Another study suggested that overexpression of histone demethylase KDM5B resulted in promoting the radioresistance of lung squamous cell carcinoma." (PMID 33304897, 2020). "However, a recent study demonstrated that patients with lung squamous cell carcinomas were observed to have a high expression of KDM5B but had a poor response to radiation, providing a clue that KDM5B could be the factor promoting radiation resistance in lung squamous cell carcinomas." (PMID 33304897, 2020).
memory impairment (1 paper, 2024). "In conclusion, KDM5B inhibitor can save the long-term learning and memory impairment caused by sevoflurane exposure in neonatal period by inhibiting KDM5B activity." (PMID 39664113, 2024).
microcephaly (1 paper, 2024). A congenital or acquired developmental disorder in which the circumference of the head is smaller than normal for the person's age and sex. "Unlike individuals with KDM5B variants, individuals with KDM5C variants frequently present with profound verbal deficiency, short stature, spasticity, and microcephaly." (PMID 39202393, 2024).
Neurodevelopmental delay (1 paper, 2024). "The most common features in individuals with KDM5B variants are neurodevelopmental delay, ID, behavioral problems, autistic behaviors, sleeping disorders, facial dysmorphology, and overgrowth." (PMID 39202393, 2024).
neuroendocrine tumor (1 paper, 2023). "KDM5B was detectable in metastatic adenocarcinoma and neuroendocrine Tumors, only a minority of this cohort (40% of cases) and further investigation is required into the role in these advanced PCa." (PMID 37152294, 2023). "Comparison of the 1057 tumors showed KDM5B was most frequently altered in neuroendocrine tumors (28.07%), followed by metastatic prostate adenocarcinoma (8.56%) and TCGA PRAD cohort (0.4%), with the majority of alterations consisting of gene amplification." (PMID 37152294, 2023). "Here we sought to extend the understanding of the individual and cooperative roles and clinical relevance of KDM1A and KDM5B in prostate adenocarcinoma and neuroendocrine tumor specimens." (PMID 37152294, 2023). "For this reason, we have completed a clinical and mechanistic analysis of KDM5B in PCa cell lines, prostate adenocarcinoma and neuroendocrine tumor patient specimens and examined the effect of individual and cooperative inhibition of KDM1A and KDM5B on androgen regulated gene expression." (PMID 37152294, 2023). "Our study quantified cytoplasmic and nuclear KDM5B expression in non-malignant prostate, prostate adenocarcinoma and neuroendocrine tumor specimens." (PMID 37152294, 2023).
osteoporosis (1 paper, 2021). A condition of reduced bone mass, with decreased cortical thickness and a decrease in the number and size of the trabeculae of cancellous bone (but normal chemical composition), resulting in increased fracture incidence. "To identify the in vivo interaction among miR‐15b, USP7 and KDM5B, we established models of osteoporosis mice and treated them with injection of miR‐15b agomir + oe‐NC, agomir‐NC + oe‐NC and miR‐15b agomir + oe‐KDM6B." (PMID 33434305, 2021).
papillary thyroid cancer (1 paper, 2021). "Accumulating evidence indicates that KDM5B knockdown could increase miR‐448 expression to impede the growth of papillary thyroid cancer cells." (PMID 33829656, 2021). "Additionally, KDM5B has been found to bind directly to the miR‐448 promoter region and thus suppress its expression in papillary thyroid cancer cells; KDM5B knockdown induced up‐regulation of miR‐448, which abolished the promoting effect of KDM5B on the malignant characteristics of cancer cells." (PMID 33829656, 2021).
prostate adenocarcinoma (1 paper, 2023). "Using cBioPortal, we analysed KDM5B gene alterations in the TCGA PRAD prostate adenocarcinoma study (n = 499), the SU2C/PCF Dream Team Metastatic Prostate Adenocarcinoma study (n = 444) and the Trento/Cornell/Broad Neuroendocrine PCa study (n = 114)." (PMID 37152294, 2023).
prostate hyperplasia (1 paper, 2023). "Recent studies utilizing a prostate specific KDM5B conditional knockout mouse model indicates KDM5B loss contributes to prostate hyperplasia." (PMID 37152294, 2023).
rectal cancer (1 paper, 2012). A primary or metastatic malignant neoplasm that affects the rectum. "Copy number increase of EFNA1 (1q22), PTGS2 (1q31.1), KDM5B (1q32.1), ESRRG (1q41), KIFC1 (6p21.32), PBX2 (6p21.32) and SOX4 (6p22.3) were only detected in rectal cancer in array CGH." (PMID 23158542, 2012).
retinal disease (1 paper, 2012). "Based on putative function and/or involvement in retinal disease, we selected 16 genes – Bach2, Cdr2, Dusp12, Esrrb, Gpsm2, Haus1, Kdm5b, Lman1, Lrp11, Lrrc2, Ncoa2, Plekha2, Ppargc1b, Trim36, Wisp1 and Zdhhc14." (PMID 22511886, 2012).
sleeping disorders (1 paper, 2024). "DD, ASD behaviors, and sleep disorders were more common in individuals with dominant disruptive KDM5B variants, while individuals with dominant missense variants presented more frequently with renal and skin anomalies." (PMID 39202393, 2024). "Individuals with dominant disruptive (nonsense, frameshift, and splicing) KDM5B variants were characterized more commonly by DD, ASD behaviors, and sleep disorders." (PMID 39202393, 2024). "Previously reported cases of bi-allelic KDM5B variants have reported that ASD, ADHD, sleep disorders, and cardiac anomalies could also be seen." (PMID 39202393, 2024).
Strabismus (1 paper, 2024). A misalignment of the eyes so that the visual axes deviate from bifoveal fixation. "Aggressive behavior, dysmorphic features, and strabismus are also common, as in individuals with KDM5B variants." (PMID 39202393, 2024).
testicular germ cell tumor (1 paper, 2020). A germ cell tumor arising from the testis. "Interestingly, KDM5B, most abundantly expressed in the normal testis, is reduced in testicular germ cell tumors." (PMID 33245716, 2020).
thyroid cancer (1 paper, 2022). "Intriguingly, we found that several histone demethylases such as KDM5B, KDM1A, KDM6B, KDM5A and KDM1B, were enriched in thyroid cancer spheres compared to non-CSCs." (PMID 35198054, 2022).